ENSG00000201151
Synonyms: LOC124900460
Gene: Small nucleolar RNA gene on chromosome 20 (35,117,136 to 35,117,207, reverse strand). Ensembl gene ENSG00000201151.
Gene Ontology:
Biological process: RNA processing
Cellular component: nucleolus
Homologues: Paralogues in human: SNORD56 (81% identical), SNORD56B (79% identical).